SOX9 (SRY-box transcription factor 9)
Diseases named in the same sentence as SOX9 in open-access papers (continued):
Sharing a sentence is not in itself a finding about the gene and the disease.
tumor (continued). "Additionally, SOX9 overexpression was correlated with lymph node metastasis and advanced tumoral stages of GC, indicating that it is related to tumor progression by promoting invasion and metastasis and with reduced disease-free survival." (PMID 31057614, 2019). "YAP-targeted therapy also diminished SOX9 expression and tumor growth in ESCC xenograft." (PMID 30401982, 2019). "Our orthotopic tumour transplantations further demonstrate that Sox9 expression is required for tamoxifen resistance in vivo, which may explain the increase in Sox9 levels observed in clinical samples from patients that have developed resistance to tamoxifen." (PMID 30622340, 2019). "Some tumor suppressors have been related with SOX9 participation in PCa." (PMID 31057614, 2019). "Additionally, some pairs of normal and tumour samples were probed for the luminal marker Muc-1 in parallel to Sox9, and the results were consistent with Sox9 being more highly expressed in tumour cells than in normal cells." (PMID 30622340, 2019). "Moreover, the mRNA expression of lncRNA DLEU2, miR-30c-5p, and SOX9 in NSCLC tumor tissues were determined by qRT-PCR." (PMID 31541993, 2019). "Likewise, within cases with venous invasion, the 5-year disease-free survival of patients with SOX9-positive tumours was 62% versus 41% of patients with SOX9-negative tumours (P = 0.02)." (PMID 31275454, 2019). "The downregulation of the N-Myc, Egr1, Sox9 mRNAs and the upregulation of Gadd45b mRNA in tumor-bearing mouse heart could conceivably be important in reducing cardiac growth and differentiation." (PMID 31851697, 2019). "However, the role of SOX9 as a tumour suppressor gene in the intestinal epithelium was questioned by some authors." (PMID 31275454, 2019). "Moreover, cells at the invasive tumor-stroma interface were also positive for Ki67 and for the inhibitor of epidermal differentiation SOX9 whereas keratinized or well differentiated tumor cells were rarely positive for these markers (asterisks)." (PMID 31867038, 2019). "This may be partly explained by the observation that estrogen reduces Sox9 expression in ER-positive cells, resulting in high Sox9 levels in ER-negative tumour cells and in tamoxifen-resistant cells, likely due to their reduced ER activity." (PMID 30622340, 2019). "ZBTB7A (Zinc Finger and BR-C, ttk and bab (BTB) Domain Containing 7A) was shown to have a crucial tumor suppressor role in the prostate by physically interacting with SOX9 and functionally antagonizing its transcriptional activity on genes involved in invasion of tumor cells." (PMID 31027362, 2019). "Opposite to the oncogenic role of SOX9 in pancreas carcinogenesis studies in tissues corresponding to later stages of tumor development have found downregulation of SOX9 and other master regulators of embryonic development such as GATA4, PDX1, PTF1a, and HNF1b." (PMID 31057614, 2019). "Overexpression of Reg IV could upregulate SOX9 expression and promote invasiveness and migration of tumor cells, and silencing of Reg IV could downregulate SOX9 and inhibit invasiveness and migration of tumor cells in MKN-45 and AGS cells." (PMID 29587675, 2018). "Application of our novel antibodies revealed that in H596 tumors from SCID mice, expression of Sox9, Slug, and Snail was relatively low, largely overlapped with E-cadherin expression, and localized primarily to tumor cells exhibiting a cobblestone-like epithelial morphology." (PMID 29928062, 2018). "The protein expression levels of COL10A1 and SOX9 were significantly correlated with tumor size (P = 0.016 and P = 0.023), tumor differentiation (P = 0.005 and P = 0.022), lymph node metastasis (P = 0.004 and P = 0.001), and serosal invasion (P = 0.001 and P = 0.015)." (PMID 30154451, 2018). "Results of another similar study showed that overexpression of SOX9 may accelerate tumor proliferation and promote oncogenesis in the prostate." (PMID 29587675, 2018).
tumor (continued). "Recent studies demonstrate that Sox9 plays active roles in tumor initiation and progression." (PMID 29970901, 2018). "In addition to Sox9+ tumour cells, we were also able to detect a strong nuclear Sox9 signal in several cells within the tumour surrounding GFAP+ cerebral tissue, both in aCP (98.4% of the patient samples) and pCP specimens (66.7% of the tumours)." (PMID 29158570, 2017). "We used 5 different Cre strains to generate tumor study cohorts: Col1a2-Cre (Cre+n = 16, Cre-n = 6), Dermo1-Cre (Cre+n = 25, Cre-n = 18), P0-Cre (Cre+n = 20, Cre-n = 15), Prx1-Cre (Cre+n = 25, Cre-n = 24), and Sox9-Cre (Cre+n = 21, Cre-n = 15)." (PMID 27191748, 2017). "Sox9 was most readily expressed in the tumor nodules the cohort, followed by CK19 and then EpCAM." (PMID 28764740, 2017). "Similarly, the expression of Sox9 in the dominant nodule was representative of the highest degree among all tumor nodules in the same liver specimen in only 14 of 22 cases." (PMID 28764740, 2017). "The cut-off value of positivity for SOX9 staining was set to 5% positive tumour cells/per 10 HPF." (PMID 29121666, 2017). "Tumor cell migration and invasion were also reduced in the SOX9 knockdown group." (PMID 29245941, 2017). "In IPMNs the rate of SOX9 positive cells decreased continuously with tumor progression." (PMID 28356064, 2017). "Indeed, we found that SOX9 knockdown strongly inhibited tumor sphere formation and anchorage-independent growth." (PMID 28912540, 2017). "Interestingly, a significant positive correlation was observed between the relative expression of linc-ROR and SOX9 in ESCC samples when compared to their matched non-tumor tissues (r = 0.562, P = 0.036)." (PMID 29237490, 2017). "In addition, we also investigated the co-expression of Sox2 and Sox9 with the oligodendrocyte transcription factor 2 (Olig2) as well as the glial fibrillary acid protein (GFAP) to define tumour surrounding cerebral microenvironment." (PMID 29158570, 2017). "Furthermore, the number of macrophages that had infiltrated the tumor stroma was correlated with SOX9 expression." (PMID 29245941, 2017). "Furthermore, SOX9 knockdown suppressed tumor metastasis and the expression of the stem cell marker ALDH1A1." (PMID 28912540, 2017). "We additionally could prove a significant correlation between high amounts of Sox9 and the appearance of Sox2 positive cell clusters within the tumour surrounding brain tissue." (PMID 29158570, 2017). "Notably, SOX9 expression values in the four CAM tumor models and in their laser-microdissected original tumors showed a similar pattern and were highly correlated with Spearman analysis (R2 = 0.910, P < 0.01)." (PMID 28304379, 2017). "However, the present known targets of miR-105 are mainly those involved in tumor behavior and malignant progression such as mRNAs of SOX9, SUZ, and NCOA1." (PMID 29282124, 2017). "Therefore, inhibited tumor growth and invasion by SOX9 knockdown shed light on regarding SOX9 as a therapeutic target for cancer." (PMID 29348895, 2017). "Thus, these genetically modified DLD-1 cells were suitable tools to evaluate the impact of an inducible activity of SOX9 on tumor cell properties." (PMID 27429045, 2016). "Furthermore, we report that SOX9 inhibits tumor development when conditionally expressed in CRC cells injected either subcutaneous or intraperitoneous in BALB/c mice as an abdominal metastasis model." (PMID 27429045, 2016). "Notably, the tumor initiating frequency was significantly higher in SOX9+ cells compared to SOX9− cells as calculated by the limiting dilution experiments." (PMID 27457505, 2016).
tumor (continued). "Furthermore, we revealed that SOX9 expression was significantly correlated with the serum OPN level in human cases, and that its efficacy in identifying SOX9 expression in the tumors was superior to conventional tumor markers such as AFP and PIVKA-II." (PMID 27457505, 2016). "Importantly, treatment with rapamycin inhibits self-renewal and tumor growth in a SOX9-dependent manner." (PMID 27571710, 2016). "Thus, CT26 cells were used to study the effect of SOX9 on tumor development in subcutaneous grafts and in a peritoneal carcinomatosis model that is the term describing widespread metastases of CRC in the peritoneal cavity." (PMID 27429045, 2016). "Furthermore, a specific inactivation of the Sox9 gene in the mouse intestine results in the formation of multiple microadenomas, thus arguing in favor of a tumor suppressor status for SOX9." (PMID 27429045, 2016). "The oncogenic role of SOX9 in ESCC progression was further examined using an in vivo tumor model." (PMID 26384302, 2015). "A similar SOX9 function had also been found in endometrial tumorigenesis, which implies that SOX9 might function as a tumor suppressor in human genital tract malignancies." (PMID 26036262, 2015). "Although this remains to be shown, these invasive cell lines with SOX10 low/SOX9 high expression might have been established by capturing or inducing invasive tumor cells that appear to be rather rare in biopsies of bulk tumor tissue." (PMID 25629959, 2015). "Sex-determining region Y-box 9 protein (SOX9) is a transcription factor that may act as both oncogene and tumor suppressor depending on tumor origin." (PMID 26036262, 2015). "An in vivo assay demonstrated that SOX9-promoted peritoneal metastasis was blocked by S100P knockdown, indicating that up-regulation of S100P expression at least partially accounts for the function of SOX9 in promotion of tumor progression in vivo." (PMID 26009899, 2015). "This was confirmed in vivo, and new direct targets of SOX9 that may mediate its function in tumor progression were identified by transcriptional profiling and chromatin-immunoprecipitation." (PMID 25885555, 2015). "Taken together, it would suggest that DNA methylation has a crucial role in malignant transformation and progression by altering the landscape of the methylome to promote tumor progression, and SOX9 is one of the targets of DNA methylation that induces cell cycle arrest." (PMID 25885555, 2015). "Moreover, p65 activation clearly induces EMT, through the up-regulation of important EMT-related proteins such as Snail, Slug, Twist, N-Cadherin, and Sox9 with tumor cells, also increasing aggressiveness and acquiring the ability to metastasize." (PMID 25974126, 2015). "We show that Sox9 is overexpressed within the lung ADC subgroup that harbors KRAS mutations, and confirm that Sox9 is overexpressed within the more malignant portions of tumor from the LSL-K-rasG12D lung ADC mouse model." (PMID 25004243, 2014). "Sox9 overexpression acts as an oncogene in several cancer types, including breast, colorectal, pancreatic, and prostate cancer and glioma, although it appears to act as a tumor suppressor in bladder cancer and melanoma." (PMID 25004243, 2014). "Strong stromal Sox9 expression may be potentially used as a prognostic marker additionally to conventional prognostic parameter when assessing residual tumor burden and response after chemotherapy." (PMID 24404438, 2013). "Sox9, Sox10 and Slug were expressed in 82–96% of the tumor cells prior to chemotherapy." (PMID 24404438, 2013). "Together, these observations suggest that SOX9 may be an attractive candidate marker that is involved in the tumor initiation and tumor progression, and it may play different roles depending on cancer types." (PMID 24188461, 2013).
tumor (continued). "Additionally, immunostaining showed more SOX9 positive cells in the higher tumor stage (T3 ~ 4) and tumor grade (G3) than in the lower tumor stage (T1 ~ 2, P = 0.03) and tumor grade (G1 ~ 2, P = 0.01), respectively." (PMID 22515642, 2012). "Furthermore, SOX9 overexpression in HCC tissues is of predictive value on tumor progression and poor prognosis." (PMID 23111165, 2012). "High levels of SOX9 were present in areas containing tumor cells in primary NSCLC tissues." (PMID 22385677, 2012). "Interestingly, SOX9 was also recently found to be expressed in NF1-related tumours, where it supports cellular survival." (PMID 21726432, 2011). "Moreover, SOX9 has shown a tumorigenicity inhibitor effect in different tumour cells, suggesting a potential tumour suppressor role." (PMID 21603610, 2011). "The epigenetic silencing of SOX9 may aid understanding as to how it contributes to tumorigenesis and tumour progression in such types of neoplasias." (PMID 18087279, 2008). "GFAP, SOX9 and type IV collagen were strongly positive in some parts of the tumours cultured for 4 and 8 weeks, while only occasional c-kit-positive areas were observed in tumours cultured for 8 weeks." (PMID 10389991, 1999). "Notably, the iRGD NPs@si‐SOX9/CL+L group exhibited the greatest reduction in tumor burden." (PMID 41270217, 2026). "Over the past two decades, altered SOX9 expression has been studied in various cancers—including colorectal, lung, laryngeal, esophageal, hepatocellular, and breast cancers—and has been associated with advanced TNM stages, higher tumor grades, lymphovascular invasion, and distant metastases." (PMID 39907598, 2025). "In GC peritoneal metastasis, SOX9 in tumor cells can inhibit T-cell cytotoxicity by promoting the secretion of interleukin 6 family cytokines and promoting the polarization of M2 macrophages, creating a microenvironment conducive to tumor growth and facilitating GC peritoneal metastasis." (PMID 40309240, 2025). "Since the influence of SOX9 inhibition on the tumor cell transcriptomes is extremely diverse and often multidirectional, it may be more promising to focus on genes and factors with narrowly targeted specific functions in the search for new therapeutic and prognostic tumor markers." (PMID 40141294, 2025). "Additionally, it is unclear whether SOX9 removal directly converts CCA lesions into HCC fate or simply eliminates CCA tumors during tumor formation, thereby allowing HCC to remain in YAP1-independent cHCC-CCA settings." (PMID 39273023, 2024). "Studies have found that tumour epithelial cells expressing specific markers (such as SOX9 and MKI67) exhibit stem cell‐like characteristics, possessing the potential for self‐renewal and differentiation, and may play a key role in the occurrence, development and metastasis of cancer." (PMID 39443302, 2024). "Thus, we counterstained the tumor cells for SOX9 after treatment with anti-KRAS antibodies." (PMID 37051535, 2023). "Notably, high SOX9 expression in pan-cancer may predict the tumor immunosuppressive microenvironment, suggesting an important role for SOX9 in tumor immune regulation." (PMID 37020558, 2023). "Thus, SOX9 may play an important role in tumor genesis and development by participating in immune infiltration." (PMID 37020558, 2023). "Expression levels of CTNNB1 (β-catenin) and SOX9, which is a transcriptional target of the β-catenin transcription factor complex, were plotted together with γδ T-cell density values determined by IHC from the same, matched tumor samples from the Scotland cohort." (PMID 37309673, 2023). "Moreover, the correlation between SOX9 expression and tumor immune cell infiltration may be related to the malignancy of the tumor." (PMID 37020558, 2023). "We analyzed the role of CD in different tumor cells and found that CD concentration-dependently decreased SOX9 protein and mRNA expression in 22RV1, PC3, and H1975, suggesting that the anticancer effect of CD may be associated with SOX9 inhibition." (PMID 37020558, 2023).
tumor (continued). "Moreover, SOX9 might play an important role in tumor genesis and development by participating in immune infiltration." (PMID 37020558, 2023). "SOX9 is a highly conserved member of the transcription factor family involved in the formation of cartilage and heart valves in mammals, contributing to the development of the pancreas, testes, liver, and other organs and resulting in tumor proliferation, invasion, metastasis, and progression." (PMID 35586685, 2022). "Thus, SOX9 gene silencing in these experiments revealed not only complete suppression of cancer cell proliferation but also effective induction of cancer cell death, resulting in complete suppression of tumor growth in an in vivo xenograft model." (PMID 35159173, 2022). "Moreover, SOX9 facilitates the neoplastic transformation of different cell types including NSCs and exerts a pro-oncogenic activity by controlling cancer stem cells (CSCs) in several tumor types, including GB." (PMID 35562901, 2022). "Therefore, we used a stemness gene associated with tumor cell heterogeneity and SOX2, SOX4, SOX9, basal cell markers KRT5, KRT14, immune genes PD-Ll and epithelial-mesenchymal transition E-cadherin to study heterogeneous cell and malignant transformation mechanisms." (PMID 36056339, 2022). "In addition to altering proliferation and symmetrical division to promote differentiation, reduction in Flii may further reduce tumor progression, whereby the exclusive nuclear SOX9 expression may increase the degradation of stabilized β-catenin." (PMID 34948000, 2021). "To determine whether CSCs involved in inflammation can also cause tumor development, we examined the expression of stem cell markers YAP1 and SOX9, and found that their expression in the cancer cells in the CC group was significantly higher than that in the normal cells of the control group." (PMID 33807620, 2021). "Also, tumor size revealed a positive correlation with SOX9 expression level since 70% of patients with microadenoma showed low SOX9 expression while 30% of patients revealed high SOX9 tumor expression." (PMID 33736633, 2021). "Thus, in this study, the expression level of SOX9 might be an acceptable marker for tumor progression in patients with CS-CCA." (PMID 35201494, 2021). "Indeed, the DRP markers such as Prom1, EpCAM, Krt19, and Sox9 detected in AH, were also induced in non-tumor liver tissue (NTL) of mice subjected to DEN injection and tumor promotion with WAD as compared to normal liver or tumor tissues, suggesting a more selective increase of DRPs in NTL." (PMID 33173221, 2020). "Conversely, dCAFs originated from tumour epithelium that has undergone an EMT and therefore highly expressed genes associated with cell differentiation and morphogenesis [i.e., scrapie responsive gene 1 (SCRG1), SRY-box transcription factor 9 and 10 (SOX9 and SOX10)]." (PMID 33066013, 2020). "Thus, SOX9 expression and function are altered in diverse human cancers, acting as an oncogene in a wide range of them, mainly through the regulation of CSCs activity, and as a tumor suppressor in specific situations." (PMID 31941916, 2020). "Finally, Western blot studies were performed to estimate the relative expression levels of the transcription factors Slug, Sox9 and Snail in parental cells and hybrid clone cells, which have all been suggested as markers for mammary stem cells and tumor-initiating cells." (PMID 32430004, 2020). "Therefore, targeting p62 or SOX9 in BCa and PCa cells that acquire inflammation-induced hormone receptor independence could prevent tumor growth or metastasis of these treatment-resistant cells." (PMID 31959131, 2020).